TRNT1 (tRNA nucleotidyl transferase 1)
Diseases named in the same sentence as TRNT1 in open-access papers (continued):
Sharing a sentence is not in itself a finding about the gene and the disease.
cancer (3 papers, 2022 to 2025). A tumor composed of atypical neoplastic, often pleomorphic cells that invade other tissues. "Genetic alteration analysis revealed significant heterogeneity in TRNT1 genetic alterations across different cancer types, highlighting the diverse nature of TRNT1 mutations in various tumour contexts." (PMID 41001838, 2025). "A pan‐cancer analysis of TRNT1 was conducted using various online bioinformatics tools, including GEPIA2, cBioPortal, TIMER2, Metascape, and UALCAN, combined with experimental validation." (PMID 41001838, 2025). "TRNT1 is highly expressed in most cancers, with significant correlation to prognosis, especially in BC." (PMID 41001838, 2025). "Subsequently, we investigated the relationship between TRNT1 gene expression and prognosis across various cancer types." (PMID 41001838, 2025). "This initial pan‐cancer study provides a relatively comprehensive understanding of the oncogenic role of TRNT1 across various cancers and highlights its potential as a biomarker for BC." (PMID 41001838, 2025). "Our analysis identified significant hypomethylation of the TRNT1 promoter in tumour tissues compared to adjacent normal tissues across multiple cancer types." (PMID 41001838, 2025). "The prognostic significance of TRNT1 expression is contingent upon the cancer type due to tissue‐specific expression patterns." (PMID 41001838, 2025). "However, the expression patterns, prognostic significance, and molecular mechanisms of TRNT1 in most cancer types remain underexplored." (PMID 41001838, 2025). "Low promoter methylation is generally associated with increased gene expression, suggesting that TRNT1 may be activated and involved in the development or progression of these cancers." (PMID 41001838, 2025). "Moreover, overexpression of TRNT1 promoted cell proliferation, while TRNT1 knockdown inhibited cell growth, supporting the notion that TRNT1 plays a pro‐tumorigenic role in cancer cell development." (PMID 41001838, 2025). "TRNT1, an RNA nucleotide transferase, plays a critical role in cellular processes and may be involved in cancer." (PMID 41001838, 2025). "However, survival analysis revealed that the prognostic value of TRNT1 expression is cancer‐type dependent." (PMID 41001838, 2025). "A comprehensive literature search revealed no prior studies that have analysed TRNT1 from a pan‐cancer perspective, and the biological impact of TRNT1 on cancer cells remains unclear." (PMID 41001838, 2025). "This suggests that TRNT1 may play a suppressive role in tumour progression in certain cancers." (PMID 41001838, 2025). "In contrast, our study found that high TRNT1 expression in BC is associated with poor prognosis, suggesting that the biological function of TRNT1 is not universal but may vary across different cancer types." (PMID 41001838, 2025).
mitochondrial disease (3 papers, 2016 to 2023). "The mitochondrial translation rate in the TRNT1 deficient patients (P1 and P2) was within the range detected in passage matched healthy and non-mitochondrial disease controls." (PMID 27370603, 2016). "Two different groups, independently, suggested a fascinating link between mitochondrial disease and interferonopathies, based on the constitutive activation of the type I IFN pathway in patients with biallelic mutations in TRNT1." (PMID 35984545, 2023). "Although TRNT1 functions both in the cytoplasm and the mitochondrion, the presence of syndromic manifestations typical of a mitochondrial disease suggests that post-transcriptional modification of mt-tRNAs, specifically CCA addition, is critical to disease pathogenesis." (PMID 27370603, 2016).
tumor (3 papers, 2021 to 2025). "Subsequently, we employed the TIMER2.0 platform to analyse the expression of TRNT1 in various tumour tissues versus normal tissues." (PMID 41001838, 2025). "The results of this study indicate that TRNT1 is overexpressed at both the mRNA and protein levels in a variety of tumours, including BC, a finding that was further validated in BC tissues and cell lines." (PMID 41001838, 2025). "Utilising the Kaplan–Meier Plotter analysis, we identified a significant correlation between TRNT1 expression and patient prognosis in several tumour types." (PMID 41001838, 2025). "Further evaluation using the UALCAN database was performed to compare the total protein expression of TRNT1 in tumour versus normal tissues." (PMID 41001838, 2025). "We analysed the genetic alterations of TRNT1 in tumour samples." (PMID 41001838, 2025). "Additionally, we integrated TCGA tumour expression data using the GEPIA2 tool to identify the top 100 genes correlated with TRNT1 expression." (PMID 41001838, 2025). "Immune cell infiltration is crucial for tumour recognition and elimination, suggesting that TRNT1 may support tumour immune evasion by reducing immune cell infiltration." (PMID 41001838, 2025).
metabolic disease (1 paper, 2016). A congenital disorder (due to inherited enzyme abnormality) or acquired (due to failure of a metabolically important organ) disorder resulting from an abnormal metabolic process. "TRNT1 (CCA-adding transfer RNA nucleotidyl transferase) enzyme deficiency is a new metabolic disease caused by defective post-transcriptional modification of mitochondrial and cytosolic transfer RNAs (tRNAs)." (PMID 27370603, 2016).
TRNT1 also shares sentences with these, for which no sentence is quoted: Arrhythmia (3 papers); congenital sideroblastic anemia-B-cell immunodeficiency-periodic fever-developmental delay syndrome (2); Anxiety (1); autoinflammatory syndrome (1); B cell deficiency (1); bladder urothelial carcinoma (1); cardiomyopathy (1); cholangiocarcinoma (1); colon adenocarcinoma (1); congenital sideroblastic anemia (1); congenital stationary night blindness (1); convulsion (1); diabetes (1); Encephalopathy (1); epilepsy (1); Epileptic encephalopathy (1); Fever (1); frontotemporal dementia (1); head and neck squamous cell carcinoma (1); hearing loss (1); inflammation (1); lung adenocarcinoma (1); MELAS (1); ovarian carcinoma (1); pancreatic insufficiency (1); panniculitis (1); pheochromocytoma (1); primary hypogonadism (1); prostate adenocarcinoma (1); prostate carcinoma (1).
A further 9 diseases each share a sentence with TRNT1 in 1 paper.